POSTN (periostin)
Diseases named in the same sentence as POSTN in open-access papers (continued):
Sharing a sentence is not in itself a finding about the gene and the disease.
bladder cancer (21 papers, 2007 to 2024). "Even though some reports indicate that periostin is overexpressed in bladder cancer and is associated with a poor prognosis in muscle-invasive bladder cancer." (PMID 36224629, 2022). "On the other hand, it was reported that a decreased expression of POSTN was associated with the progression of bladder cancer in humans." (PMID 32987711, 2020). "In conclusion, periostin is a component of bladder cancer cells associated with poor clinical outcome, and EVs can transfer oncogenic molecules such as periostin to affect the tumor environment and promote cancer progression." (PMID 26981774, 2016). "In the current study, we identify epithelial periostin expression as a feature of bladder carcinoma associated with poor patient outcomes and characterize its oncogenic properties." (PMID 26981774, 2016). "Spliced variants of periostin, an EXM protein, have been detected in bladder cancer tissues and cell lines." (PMID 39132499, 2024). "Only a few reports in bladder cancer and osteosarcoma have shown POSTN as a tumor-inhibiting factor." (PMID 35163164, 2022). "In contrast, the results of previous studies in search of periostin’s role in urinary bladder cancer are controversial." (PMID 35850759, 2022). "In contrast, in bladder cancer, periostin suppressed Akt phosphorylation, followed by downregulation of Twist, an E-cadherin negative regulator, leading to an increase in E-cadherin expression and a decrease in bladder cancer cell invasion." (PMID 36224629, 2022). "Furthermore, periostin, which functions as a ligand for alpha V/beta 3 and alpha V/beta 5 integrins to support adhesion and migration of epithelial cells and is associated with poor clinical outcome in bladder cancer, was also identified in T-24-derived ectosomes." (PMID 34202855, 2021). "Upregulation of periostin (POSTN) has been observed in many cancer types, such as ovarian, pancreatic, breast, and bladder cancer." (PMID 30867659, 2019). "Immunohistochemically, analysis demonstrated a strong staining of POSTN in the stroma of normal bladder, while it was mostly attenuated in bladder cancer tissues." (PMID 29946533, 2018). "The activation of the ERK signal pathway by periostin consequently leads to bladder cancer cell invasion and migration." (PMID 26981774, 2016). "In our study, we find that periostin knockdown cells have lower expression of integrinβ1, suggesting a positive feedback regulatory pathway between periostin and integrin β1 in bladder cancer cells." (PMID 26981774, 2016). "While periostin's pro-cancer properties have been suggested in many cancers, the situation is less clear in bladder cancer." (PMID 26981774, 2016). "The overexpression of periostin and its secretory nature make it an attractive potential body fluid biomarker for bladder cancer." (PMID 26981774, 2016). "Elevated POSTN transcription in the high grade BC lines prompted us to examine its biological function, and we chose to knock down periostin by shRNA in the two bladder cancer cell lines in which it is most abundant, TCC-SUP and J82." (PMID 26981774, 2016). "This differential expression contradicts reports that periostin is down-regulated in invasive bladder cancer." (PMID 26981774, 2016). "In one study, wild-type periostin was reduced by downregulation or alternative splicing, particularly in isoforms lacking exon 18, and was strongly associated with bladder cancer progression." (PMID 39132499, 2024). "Overexpression of periostin is associated with enhanced invasiveness in most cancers but not in bladder cancer." (PMID 36224629, 2022). "In addition, increased periostin expression was detected in the bladder cancer cell lines MIBC, J82, TCC-SUP, and UMUC3." (PMID 36224629, 2022). "In bladder cancer, periostin antagonizes EMT by downregulating Twist." (PMID 32793478, 2020). "Periostin resulted down-expressed in PCa but overexpressed in bladder cancer." (PMID 32793478, 2020).
bladder cancer (continued). "Thus, while POSTN expression was detected in 100% normal bladder tissues, only a 33% of grade 3 bladder cancer expressed POSTN." (PMID 29946533, 2018). "Periostin also suppresses cell migration in human bladder cancer cells via a TAB 1(TGF-beta activated kinase)/TAK1 (TGF-beta activated kinase 1) signaling pathway, providing a possible explanation for its potent role in controlling the migration of suture-derived cells." (PMID 29665811, 2018). "In addition, immunohistochemical staining of a bladder cancer tissue microarray revealed that the presence of periostin in MIBC cells is correlated with worse prognosis." (PMID 26981774, 2016). "In contrast, periostin's role in bladder cancer has been suggested to be suppressive." (PMID 26981774, 2016). "In this study we provide evidence of periostin's role in the promotion of bladder cancer." (PMID 26981774, 2016). "In order to examine the functional significance of secretory periostin to bladder cancer, we treated three bladder cancer cell lines with human recombinant periostin protein (rPOSTN) and measured the ability of the cells to invade through basement membrane extract in a transwell invasion assay." (PMID 26981774, 2016). "In addition, our discovery of high periostin levels in bladder cancer EVs suggests its potential as a urinary biomarker of disease recurrence or progression." (PMID 26981774, 2016). "Rab27a functions as a vesicle docker at the peripheral cytoplasm; a similar pattern of peripheral periostin expression in bladder cancer cells might also suggest a role in EV secretion." (PMID 26981774, 2016). "Here we find that knockdown of POSTN reduced integrin β1 transcription but left the rest of the integrin family unchanged, suggesting that integrin β1 might be involved in periostin-mediated signaling in bladder cancer cells." (PMID 26981774, 2016). "In short, the abundance of periostin in bladder cancer urinary EVs suggests its potential utility as a biomarker, and a deeper investigation of EV periostin levels in bladder cancer recurrence and stage or grade progression may be warranted." (PMID 26981774, 2016). "Targeting this periostin-mediated pathway, perhaps through inhibition of integrinβ1 and/or the ERK signal, might be beneficial for those bladder cancer patients who have elevated urinary EV periostin." (PMID 26981774, 2016). "To further test whether periostin expression levels in bladder cancer can predict patient outcome, we performed immunohistochemical staining in a tissue microarray (TMA) composed of 84 NMIBC and 64 MIBC samples." (PMID 26981774, 2016). "In summary, we have identified periostin as a feature of bladder carcinoma epithelial cells and have provided evidence that POSTN up-regulation may be an important driver of bladder cancer." (PMID 26981774, 2016). "Therefore, future studies should determine whether CHI3L1, through its regulation of POSTN expression and function, affects the response of patients with bladder cancer to chemotherapeutic drugs." (PMID 37958973, 2023). "However, others have reported that POSTN might inhibit the invasion and metastasis of bladder cancer cells." (PMID 35163164, 2022). "However, other studies suggest an opposite role for POSTN in the development of bladder cancer." (PMID 29946533, 2018). "Moreover, the ectopic overexpression of POSTN in bladder cancer cells might enforce cellular environment alterations that would not occur in the normal physiological setting." (PMID 26981774, 2016). "However, the downregulation of POSTN mRNA is significantly related to high grade bladder cancer." (PMID 26023718, 2015). "Periostin affects EMT and cell invasiveness differently in prostate and bladder cancer cells." (PMID 36224629, 2022). "By contrast, in bladder cancer tissues, the canonical POSTN isoform is not expressed and only some alternatively spliced isoforms can be detected." (PMID 29946533, 2018).
bladder cancer (continued). "Unlike most tumors, POSTN expression appears to be downregulated in bladder cancer compared with normal tissue." (PMID 29946533, 2018). "Periostin up-regulation is observed in both MIBC cell lines and clinical tissue samples, periostin down-regulation via gene knockdown suppresses bladder cancer cell invasion, and treatment with rPOSTN promotes bladder cancer cell invasion." (PMID 26981774, 2016). "However, no study has provided information on stromal periostin expression in bladder cancer." (PMID 35850759, 2022). "In order to determine whether the periostin cargo borne by EVs contributes to this effect, we treated a low-grade bladder cancer cell line, 5637, with EVs derived from TCC-SUP cells with and without POSTN knockdown." (PMID 26981774, 2016).
breast tumor (20 papers, 2006 to 2025). "In primary breast tumours, POSTN causes up-regulation of vascular endothelial growth factor receptor (VEGFR)-2 in endothelial cells." (PMID 17014703, 2006). "In addition, this study found that POSTN promoted LOX activation in the breast tumor model and the deficiency of POSTN decreased the immunosuppression functions related to activating ERK and AKT in MDSCs and impaired the MDSCs‐induced tumor metastases." (PMID 39947253, 2025). "Increased matrix stiffness activates YAP, promoting the secretion of periostin (POSTN) in CAFs, which in turn augments the matrix rigidity of mammary glands and breast tumour tissues by facilitating collagen crosslinking." (PMID 40243781, 2025). "The the pro-metastatic role of POSTN is limited to ER-negative breast cancer patients, which indicates that POSTN is a potential target for the prevention and treatment of breast tumor metastasis." (PMID 36593497, 2023). "More recently, we demonstrated that stromal POSTN distribution in metastatic breast tumors of the lung is dramatically altered following TIMP2 treatment." (PMID 31882975, 2019). "Periostin promotes the pulmonary accumulation of MDSCs during the early stage of breast tumor metastasis." (PMID 30792719, 2019). "Current reports have demonstrated that periostin plays a critical role in the acquisition of most of these hallmarks of breast tumor progression." (PMID 29161296, 2017). "In a breast tumor model in vivo, the administration of anti-POSTN neutralizing antibodies inhibited the proliferation, migration, and invasion of breast tumor cells, as well as the differentiation of osteoclasts." (PMID 29065446, 2017). "A recent report demonstrated that stromal periostin is a key limiting factor regulating lung metastasis of mouse breast tumors." (PMID 29161296, 2017). "In conclusion, our findings indicate that breast tumor progression is accompanied by increased periostin expression." (PMID 29161296, 2017). "Here, a deposition of periostin was revealed not only in the primary breast tumor but also even more pronounced in the lung metastasis." (PMID 26539408, 2015). "Taken together, POSTN-expressing MCF-10A cells have the ability to enhance breast tumor growth and metastasis." (PMID 24009721, 2013). "Fibroblast-derived POSTN was identified to be a limiting factor for lung metastasis of mouse breast tumors and is required for murine breast CSC maintenance." (PMID 24009721, 2013). "POSTN−/− murine primary breast tumor cells fail to form tumorspheres, but this phenotype can be rescued by adding POSTN protein to primary cultures." (PMID 24009721, 2013). "This study highlights that ANRIL exists in different subcellular locations in breast tumors, which may affect its functionality, for example whether nuclear ANRIL is associated with increased POSTN expression in malignant epithelial cells." (PMID 31572679, 2019). "In periostin-deficient MDSCs, the activation of extracellular regulated protein kinase (ERK), PKB and STAT3 and immunosuppressive functions are decreased, which accelerate breast tumor growth." (PMID 30792719, 2019). "A recent study suggested that periostin deficiency decreases the immunosuppressive functions of myeloid-derived suppressor cells (MDSCs) during tumor progression, impairing the MDSC-promoted lung metastasis of breast-tumor cells." (PMID 30131847, 2018). "Periostin may play an important role in the progression of breast tumor, and epithelial periostin expression may serve as a new parameter for prediction of prognosis in patients with IBC." (PMID 29161296, 2017). "Interestingly, POSTN is also able to regulate the immunosuppressive function of immature myeloid cells in ER-negative breast cancer patients and thus promote premetastatic niche formation in the lungs during breast tumor metastasis." (PMID 33513753, 2021). "Furthermore, our study suggests that POSTN could represent a new potential target for the prevention and treatment of breast tumor metastasis." (PMID 33513753, 2021).
breast tumor (continued). "Even though the fold change of BCAS4 was less than the other three up-regulated proteins (periostin, ATAD2, and Ki-67), it was still attractive because BCAS4 was significantly increased in breast tumors compared to normal tumors reported by UALCAN." (PMID 37922300, 2023). "Mass spectrometric data from 125 breast tumour samples showed CTHRC1, POSTN and MMP13 to all be significantly higher in breast tumour tissue relative to normal while SFRP4 and FNDC1 levels were unaffected." (PMID 36190948, 2022). "Therefore, further studies are required to investigate if POSTN positivity is correlated with VEGFR-2 expression, thereby providing a molecular mechanism that links POSTN to endocrine resistance for ER-positive breast tumours." (PMID 17014703, 2006). "The absence of significant increase in POSTN expression in breast tumors contrasts with the conclusions from a previous study in which expression in tumors was compared to the low level of POSTN mRNA in primary mammary epithelial cultures as reference for normal breast tissue." (PMID 18086302, 2007).
head and neck cancer (20 papers, 2011 to 2024). A primary or metastatic malignant neoplasm affecting the head and neck. "POSTN (Periostin) secretion from cancer-associated fibroblast (CAF) promotes cancer stemness in head and neck cancer." (PMID 38027033, 2023). "It has been recently demonstrated that periostin is associated with metastasis in head and neck cancer, and that this protein directly accelerated the growth, migration and invasion of cancer cells." (PMID 27358011, 2016). "Nonetheless, rapamycin and other FDA approved rapalogs constitute a viable therapeutic strategy for diseases and pathologies associated with increased levels of Periostin, including colorectal, prostate, breast, and head and neck cancers." (PMID 24349533, 2013). "Tumor stroma CAF-derived POSTN has been shown to promote head and neck cancer stemness by activating protein tyrosine kinase 7-Wnt/β-catenin signaling." (PMID 36550569, 2022). "Several studies revealed that Periostin is upregulated in a wide variety of cancers such as colon, pancreatic, ovarian, breast, non-small cell lung, and head and neck cancer." (PMID 25221676, 2014). "The literature reports the involvement of POSTN in head and neck cancer metastases." (PMID 39195230, 2024). "In addition, POSTN expression in head and neck cancer has been shown to correlate with VEGF-C expression, both in tumor tissue and serum." (PMID 29946533, 2018). "In some studies, by comparing three separate comprehensive gene expression omnibus (GEO) databases, researchers claimed that overlapping differentially expressed genes like SPP1, POSTN, and COL1A2 could be used as potential diagnostic indicators of head and neck carcinoma." (PMID 33134377, 2020). "A correlation between POSTN and VEGF-C expression has already been reported in patients with head and neck cancer." (PMID 35567669, 2022). "In addition, CAF-derived POSTN, induced by TGF-β3, was able to accelerate the migration and invasion of head and neck cancer cells." (PMID 29946533, 2018).
cardiac hypertrophy (19 papers, 2014 to 2024). "Our results also show that cardiac hypertrophy is suppressed by PRMT5 deficiency specifically in periostin-positive cells." (PMID 38503742, 2024). "As a secretory protein, periostin in CF might affect CM functions in a paracrine-dependent manner since we found that loss of periostin ameliorated cardiac hypertrophy in diabetic mice." (PMID 37993768, 2023). "POSTN itself has been implicated in inducing cardiac hypertrophy in animal and human studies." (PMID 37939043, 2023). "A novel immunomodulator was then found to alleviate cardiac hypertrophy and fibrosis through the reduction of periostin." (PMID 38255321, 2024). "In line with these previous studies, our results indicate that PRMT5 in periostin-expressing fibroblasts plays a key role in the development of cardiac hypertrophy." (PMID 38503742, 2024). "The knockout of TGF-β receptors 1/2 and β-catenin in periostin-expressing fibroblasts significantly reduced cardiac hypertrophy induced by pressure overload." (PMID 38503742, 2024). "Mice treated with an Ang II infusion developed LV hypertrophy and fibrosis, and an increase in expression of periostin by cardiac tissue was reported." (PMID 38279150, 2024). "Treatment of HCM mice with TGF-β-neutralizing antibodies markedly reduces the expression of periostin, which promotes differentiation into fibroblasts and improves cardiac hypertrophy." (PMID 39165751, 2024). "Transcriptional analysis of heart revealed that cardiac hypertrophy, fibrosis, inflammation and oxidative burst were intensified in diabetic mice with periostin overexpression." (PMID 37993768, 2023). "Periostin, which is highly upregulated in fibrotic tissue, plays a critical role in cardiac hypertrophy and ventricular remodeling." (PMID 37507917, 2023). "The level of periostin in the nasal secretion of children with hypertrophies (n=9) was 21.6 [10.7; 1516.8] ng/mg, which was significantly higher than that in children with polyposis (n=6): 0.17 [0.001; 0.32] ng/mg; W=48.0; p=0.02." (PMID 34796003, 2021). "Several recent studies also revealed that periostin levels were elevated during cardiac hypertrophy." (PMID 29872491, 2018). "Elevations of Periostin have already been identified in other cardiac diseases, including myocardial hypertrophy and ventricular remodelling where a fibrotic mechanism was identified." (PMID 30213070, 2018). "PostnMCM mice are frequently used in fibroblast-specific molecular analysis of pathological cardiac fibrosis, both because pressure overload induces pathological cardiac hypertrophy and fibrosis, and because periostin is preferentially expressed in activated cardiac fibroblasts." (PMID 38503742, 2024). "Several studies also revealed that periostin was elevated during cardiac hypertrophy." (PMID 29872491, 2018). "TGFBI over-expression, which was deposited within the ECM, induced a mild degree of concentric cardiac hypertrophy reminiscent of a nearly identical increase of baseline cardiac hypertrophy observed in periostin heart-specific over-expressing mice at 32 weeks of age." (PMID 28750100, 2017). "In contrast, periostin deletion decreases cardiac hypertrophy and fibrosis after pressure overload." (PMID 28767701, 2017). "However, HFD and STZ promoted cardiac hypertrophy, fibrosis and oxidative stress in control mice only, but not in the periostin-deficient mice, as evidenced by H&E staining, sirius red staining and DHE staining." (PMID 37993768, 2023). "Periostin (Postn) is an ECM protein expressed predominantly by fibroblasts and plays an key role in cardiac hypertrophy and fibrosis following myocardial infarction." (PMID 31704980, 2019). "The in vivo results revealed that TAC prominently induced cardiac dysfunction, left ventricular dilation, myocardial hypertrophy, and elevated myocardial collagen deposition, accompanied with increased fibrotic markers including α-smooth muscle actin (α-SMA) and periostin." (PMID 31178725, 2019).